CXCL1 (C-X-C motif chemokine ligand 1)
Diseases named in the same sentence as CXCL1 in open-access papers (continued):
Sharing a sentence is not in itself a finding about the gene and the disease.
cancer (continued). "Similarly, the overexpression of CXCL1, CXCL6, or CXCL12 has been shown to increase epithelial cell migration, proliferation, and growth, albeit in many cancer models." (PMID 35328555, 2022). "When querying the Cancer Genome Atlas data set, we found positive correlations between IL1B expression and infiltration of immunosuppressive PMNs and expression of their chemoattractant, CXCL1, and PDCD1 expressions in patients with KM-LUAD." (PMID 35471938, 2022). "Not less important is CXCL1 production by cancer cells in bone metastasis, as CXCL1 stimulates cancer cell proliferation, as well as participating in bone remodeling during bone metastasis formation." (PMID 35457023, 2022). "The increase in CXCL1 and decrease in CD206+ cells would seem to reflect acute inflammation; however, this may also contribute to cancer progression." (PMID 35740353, 2022). "Therefore, in cancer cells, pro-inflammatory cytokines such as IL-1β and TNF-α can only increase the stability of CXCL1 mRNA." (PMID 35054978, 2022). "In our work, we showed the exposure of calreticulin in a subpopulation of ferroptotic cells shortly before their rupture, as well as ATP, HMGB1, CXCL1, TNF and IFN-β release in the course of a drug- and genetically induced models of ferroptosis in cancer cells." (PMID 35760796, 2022). "This association of PTGS2 with inflammatory cytokine expression extends to established cancer; analysis of mRNA-seq data from the Cancer Genome Atlas (TCGA) dataset showed positive correlations of PTGS2 expression with IL1B, IL6, IL8, and CXCL1 in all cancer types." (PMID 33730589, 2021). "CXCL1 expression was higher in cancer tissues than in adjacent tissues but did not affect patient prognosis, specifically OS." (PMID 34218518, 2021). "Furthermore, the UALCAN dataset, which is based on publicly available cancer omics data (TCGA and MET500), was used to estimate the expression of CXCL1 in BRCA based on different subclasses." (PMID 33959656, 2021). "We propose that muscle-derived IL10, CXCL1 and CCL4 are, at least in part, responsible for the exercise-mediated upregulation of CASP3 and 7 gene expression and consequently their increased protein levels in PC and other cancer cells." (PMID 34359731, 2021). "Notably, it has been reported that the axis connecting CXCL1 and its receptor, CXCR2, a G protein-coupled receptor, plays significant roles in mediating the communication between cancer cells and the microenvironment of gastric and bladder tumors." (PMID 33941851, 2021). "The effect of hypoxia on the expressions of CXCL1 and CXCL2 depends on the type of cancer." (PMID 33467722, 2021). "These evidences suggest that CXCL1, CXCL2, and CXCL3 may be indirectly involved in the genesis and progression of carcinoma through the mobilization of human immune cells." (PMID 34269159, 2021). "Luciferase-imaging experiments further revealed that XIAOPI formula or CXCL1 knockdown could significantly block TAMs-induced cancer cells metastasis, and the anti-metastasis effects of XIAOPI formula were abrogated by CXCL1 overexpression in TAMs." (PMID 32213179, 2020). "The best performing model for discrimination between benign tumors and borderline tumors + cancer was a 6-biomarker combination (HE4, CA125, ITGAV, CXCL1, CEACAM1, IL-10RB) and age (AUC 0.868, sensitivity 0.86 and specificity 0.82, p = 0.016 for comparison with the reference model)." (PMID 33075095, 2020). "Importantly, although TFF1 is predominantly expressed by cancer cells, the authors detected CCL20, CXCL1, and IL-8 in cancer cells and also in the surrounding stroma." (PMID 32373132, 2020). "For example, TAMs-secreted CXCL1 could recruit myeloid-derived suppressor cells (MDSCs) into the TME, which secreted chemokines including S100A8/9 that enhanced cancer cell survival, chemoresistance, metastasis, and pre-metastatic niche formation." (PMID 32300100, 2020).
cancer (continued). "Bone marrow-derived macrophage efferocytosis of apoptotic cancer cells, but not apoptotic normal cells, resulted in increased gene expression of Cxcl1, Cxcl4, Cxcl5, and IL-6 inflammatory cytokines in comparison with peritoneal macrophages." (PMID 32059476, 2020). "Notably, the proliferation-promotion effects of TAMs-CM-treated HSPCs on cancer cells were significantly inhibited following XIAOPI administration, and were subsequently reversed by CXCL1 overexpression." (PMID 32213179, 2020). "TRAIL treatment was also shown to enhance pro-inflammatory cytokine and chemokine production, including IL6, IL8, MCP1, CXCL1, and MIF, in various cancer cell types independent from TRAIL sensitivity although cytokines levels were higher in resistant cancer cells." (PMID 31333662, 2019). "Overexpression of CXCL1 and CXCL8 in cancer cells correlated with poor prognosis in GC patients." (PMID 31147602, 2019). "Data from studies of the bladder and other cancers implicate IL6, IL8, CXCL1, and PAI1 as factors that may play a role in the ability of the adipose CM and ASC CM to alter the migratory potential of the T24 cells." (PMID 29887999, 2018). "The overall survival rate of all patients (n = 143) with CXCL1-positive cancer cells was significantly poorer (p<0.001) than that of the patients with CXCL1-negative cancer cells (n = 120)." (PMID 28575019, 2017). "In a breast cancer model, CXCL1/2 is produced by cancer cells and serves as a chemoattractant for myeloid cells that are recruited to the lungs, where they produce S100A8/9 to enhance cancer cell survival at the metastatic site." (PMID 28210073, 2017). "The multivariate analysis revealed that CXCL1 expression in cancer cells was not an independent prognostic factor." (PMID 28575019, 2017). "Mostly recruited following a CXCL5 gradient (whose human orthologues, CXCL1 and IL‐8, are expressed by cancer cells), these immunosuppressive cells could in turn promote EMT‐like changes in cancer cells, via multiple pathways comprising TGF, EGF, and HGF." (PMID 28599100, 2017). "To investigate the relevance of CXCL1-dependent ASC trafficking to cancer progression, we first demonstrated that proliferation of CXCL1-sh-RM1 and control-sh-RM1 cells was non-distinguishable at both high serum and low serum concentrations." (PMID 27241286, 2016). "This analysis revealed that CXCL1 expression was high in malignant epithelium of three out of three patients who subsequently died from cancer, while it was variable in other cases and absent in normal prostate controls." (PMID 27241286, 2016). "In accordance with previous reports in cancer cells, we found that miR-103 represses the translation of KLF4 mRNA by direct interaction with a conserved binding site in its 3′UTR, which results in NF-κB-mediated upregulation of CXCL1 in ECs48." (PMID 26837267, 2016). "Which signalling pathways are activated by CXCL1 through CXCR2 in dendritic cells is yet unknown, however studies in different cell types, such as cancer cells, show that CXCR2 signalling can activate NF-κB, STAT3 and the ERK pathways." (PMID 22125641, 2011). "Upregulation of CXCL1 and CXCL3 has previously been observed in CRCs and other cancer types." (PMID 17201907, 2007). "Notably, the recruitment mechanisms (CCL15 vs CXCL5/CXCL1/8) and effector molecules (VEGFC-dominant vs MMP9/VEGFA-cooperative) display cancer-type specificity, suggesting evolutionary selection for distinct molecular implementations of a conserved TANs-lymphatic metastasis principle." (PMID 40739091, 2025). "NK cells with reduced anti-cancer functions in the immunosuppressive lung tumor microenvironment acquire pro-cancer properties and begin to produce and secrete VEGF and CXCR2 ligands such as CXCL1, CXCL2, and CXCL8/IL-8 as well as IL-6, CCL2, matrix metalloproteinases (MMP), and many others." (PMID 38673949, 2024).
cancer (continued). "Mechanistically, cancer intrinsic TNFRSF14 phosphorylates FAK at Y397 and activates its downstream NF-κB signaling, which not only enhances the tumorigenicity of GBM cells, but promotes the recruitment of anti-inflammatory TAMs through elevating CXCL1 and CXCL5 secretion from GBM cells." (PMID 39085878, 2024). "Thus, we identified two biomarkers (CXCL1 and BCL6) for the diagnosis of colitis-related cancer." (PMID 39582536, 2024). "CXCL1 showed non-significant levels of detection in the cancer group compared to the control group." (PMID 39523395, 2024). "Furthermore, CXCL1 secretion in the cancer cells was not affected by Adam17 knockout, indicating that CXCL1 originates from the macrophages in our cocultures." (PMID 35998057, 2022). "CXCL1, LCN2, S100A8, and IDO1 may play essential roles in cancer progression." (PMID 34306038, 2021). "Since there is discrepancy regarding the anti-cancer impact of CXCL1 and CCL4 between our results and some data from the literature, it is of interest whether the site of expression determines different biological functions of CXCL1 and CCL4." (PMID 34359731, 2021). "CXCL1/CXCR2-mediating signaling cascades, such as PI3K/Akt, mitogen-activated protein kinase (MAPK), and nuclear factor kappa-light-chain-enhancer of activated B cells (NF-κB), have been considered the regulatory signaling pathways for migration and invasion in several cancer cells." (PMID 34760697, 2021). "* Via physical contacts with cancer cells and through secreted factors, theyincreased CSC proportions, as well as EMT and migration.* The activities of the myeloid cells were mediated by or connected to solublefactors such as TNFα, IL-6 and ELR+ CXC chemokines (e.g., CXCL8 and CXCL1)." (PMID 33585241, 2020). "In parallel to CXCL8, CXCL1 also contributed to stemness, but its impacts were mostly found in regulation of EMT-related processes, migration and invasion; in this respect, CXCL1 was found to act in an autocrine manner and/or to be secreted by macrophages in vicinity of the cancer cells." (PMID 33585241, 2020). "In addition to these chemokine receptors, chemokine ligands such as CXCL1, CXCL2, CXCL5, CXCL6, CXCL8, and CXCL9 have been also significantly correlated with poor survival and metastasis in several cancers by recruiting MDSCs and suppressing the antitumoral activity of CD8+ T effectors cells." (PMID 32719800, 2020). "However, the chemokines and their receptors that particularly stimulate tumorigenesis, including CCR7, CXCL1, CXCL8, and CXCL12/CXCR4, could, consequently, act as poor prognostic markers for cancer patients." (PMID 31991604, 2020). "Indeed, Cxcl1 expression was downregulated by Kras or Chuk silencing and IL-1β induced Cxcl1 expression by two different cancer cell lines and Ppbp by LLC cells (MC38 cells do not express Ppbp25)." (PMID 29445180, 2018). "However, the abundance of CXCL1 among TAM-secreted chemokines and its level relative to cancer cells remain largely unknown." (PMID 30158589, 2018). "Furthermore, because an NF-κB inhibitor attenuated CXCL1-induced cell invasion in CXCR2 positive cells, our results suggest that the CXCL1-CXCR2 axis may accelerate cancer progression by potentiating NF-κB signaling." (PMID 24376747, 2013). "Moreover, in line with the results of chemotherapy, the expression of CXCL1/2 and CFB in macrophages was significantly increased in response to local radiation, evidenced by data from immunofluorescence, Western blot, scRNA-Seq, and ELISA in mouse cancer models." (PMID 41480760, 2026). "Importantly, the increase in the expression of CXCL1 and other CXCR2 ligands may not be a mechanism of chemoresistance but only a marker of chemoresistance in some cancers associated with the induction of TNF-α expression by chemotherapeutics, e.g., docetaxel." (PMID 40427171, 2025).
cancer (continued). "Furthermore, the CXCL1/CXCR2 axis can induce PMN-myeloid-derived suppressor cells (MDSCs) accumulation in the TME and induce CD8+ T cell exhaustion, which may offer a potential therapeutic strategy for cancer therapy." (PMID 38515019, 2024). "Interestingly, the genes coding for chemokines such as CXCL1, CXCL2, CXCL3, and CXCL8 (IL-8) were strongly upregulated in CD4+ T cells co-cultured with cancer cells only, further suggesting the direct influence of cancer cells on chemokine expression in CD4+ T cells." (PMID 34439305, 2021). "However, CXCL1 secretion appeared to be cancer specific, whereas IL-6 did not." (PMID 29360827, 2018). "We applied immunohistochemical staining to determine the mRNA expressions of CXCL1 and BCL6 in nontumor adjacent, UC and cancer tissues." (PMID 39582536, 2024). "Despite this, a comprehensive summary of the involvement of C-X-C motif ligand 1 (CXCL1) chemokine (also known as growth-regulated gene-α (GRO-α), melanoma growth-stimulatory activity (MGSA)) in cancer processes is lacking." (PMID 37408240, 2023). "Fibrocytes secrete only IL23 and IFNγ, which were suppressed upon co-culture, whereas cancer cells or fibrocytes secrete CCL5, IL-1ra, CD54, CXCL10, MIF, CXCL1, IL-6, and IL-8, which was not affected by co-culture." (PMID 36241617, 2022). "According to the literature, CXCL1, IL10 and CCL4 are more or less well described myokines, but as muscle-derived factors no significant anti-cancer effect has been attributed to them yet." (PMID 34359731, 2021). "The overall survival of patients with CXCL1 and CXCR2-positive cancer was poorer than that of the patients with negative cancer." (PMID 28575019, 2017). "Additionally, an analysis of COAD and adjacent non-cancerous tissue samples from the TCGA database confirmed significant increases in CXCL1, CXCL8, CXCL9, and CXCL11 in cancer tissues, while CCL22 showed no significant change." (PMID 38791448, 2024). "However, for the T47D cancer cells, even though WEW did not increase senescence per se, a significant upregulation of the SASP factor CXCL-1 was observed." (PMID 38696307, 2024). "Also, unlike the effect on macrophage-induced cancer cell invasion, treatment with rCSF-1 alone or in combination with rHB-EGF did not increase the expression of CXCL1." (PMID 35998057, 2022). "Different previous studies have demonstrated the role of CXCL1’s up-regulation in CRC metastasis and progression, however, none of these studies generalized CXCL1 in CRC patients of different clinicopathological features (different races, cancer stages, genders, age groups, and body weights)." (PMID 34473751, 2021). "Pretreatment of Tregs with TAM/CXCL1 signal did not affect the proliferation activities of the co-cultured CD8+T cells, but it significantly induced their apoptosis and cytolytic function inactivation, leading to the decreased cytotoxic effect of CD8+ T cells on cancer cells." (PMID 34461944, 2021).
bacterial infection (43 papers, 2011 to 2025). "Nevertheless, in some situations type 1 IFNs can also increase the host susceptibility to subsequent bacterial infection through impaired macrophage recruitment with a reduced CXCL1 and CXCL2 transcription and a reduced IL17 production." (PMID 32546263, 2020). "For instance, Setdb2, the family member most closely related to Setdb1, mediates virus-induced susceptibility to secondary bacterial infection by regulating CXCL1 transcription." (PMID 27349785, 2016). "Only the cytokines IL-17 and the murine CXCL-8 homolog CXCL-1 were decreased on mRNA and protein levels during bacterial infection in mCLCA3-deficient mice compared to wild-type controls." (PMID 25033194, 2014). "Influenza virus was able to induce similar anti-inflammatory function in AMs with decreased CXCL1 production and neutrophils recruitment via type I IFN pathway, leading to an increased susceptibility to super bacterial infection." (PMID 40624927, 2025). "Analysis of proinflammatory cytokines and chemokines at different time points showed significant upregulation of Tnf, Mmp14, Il1b, Il1a, Il17ra, Cxcl1, Cxcl2, Ccrl2, Ccl3, Ccl4, and Ccl9 after bacterial infection." (PMID 41117166, 2025). "We used qRT-PCR to quantify the expression of inflammatory genes commonly elevated in bacterial infections including the chemokine Cxcl1, cytokines (Il22, Il17a, and Il6), and the bactericidal antimicrobial peptide Reg3g." (PMID 41502946, 2025). "In bacterial infections, a CARD9 deficiency results in a decrease in inflammatory cytokines (IL-1β, IL-6, and TNF-α) and chemokines (CXCL1, CXCL2, and CXCL5)." (PMID 38473845, 2024). "Bacterial infection significantly upregulated mRNA expression levels of Isg15, Mx1, Mx2, Irf-3, Irf-7, Tlr-2, Tnf-α, Cxcl-1, and Il-6 genes." (PMID 37929187, 2023). "Previous studies have shown that Cxcl1/Cxcl2/Il1b axis in neutrophils plays a major role in inflammatory response during bacterial infections." (PMID 38149246, 2023). "Setdb2 is upregulated and induces the repressive H3K9me3 of at Cxcl1 promoter, leading to reduced neutrophil infiltration and attenuated host defense against secondary bacterial infection." (PMID 37143582, 2023). "Respiratory epithelial cells producing low levels of DNMT3B expressed higher levels of CXCL1 and CXCL8, which was associated with increased neutrophil recruitment during bacterial infections." (PMID 36078063, 2022). "Our work shows that during E. coli K1 infection of the brain, astrocytes are activated by microglia-derived TNF-α, which then secrete chemokine CXCL1 to promote neutrophil recruitment, which is required to control bacterial infection." (PMID 35742984, 2022). "This indicates that early neutrophil recruitment into the lung, mediated by a relatively small amount of transcytosed CXCL1 originating from the alveoli, is necessary to efficiently contain bacterial infections and subsequent pathogen dissemination into the circulation." (PMID 40413164, 2025). "CXCL1 is known to induce neutrophil influx during bacterial infections." (PMID 38474145, 2024). "The GSDMD−/− mice presented decreased IL-1β and increased Cxcl1 secretion following S. aureus infection, suggesting that upon S. aureus challenge, promotion of IL-1β production or inhibition of Cxcl1 may be the key for the protective effect of GSDMD during bacterial infection." (PMID 34011393, 2021). "We also determined the levels of the chemokines C-X-C motif ligand 1 (CXCL1) and CXCL2, both of which are important for neutrophil attraction during bacterial infection." (PMID 40359428, 2025). "The researchers found that CCR2+ monocytes produced high levels of CXCL1, which directly recruited CXCR2-expressing neutrophils to the lungs, contributing to the host defense against bacterial infection." (PMID 38596679, 2024).